CXCR2 (C-X-C motif chemokine receptor 2)
Diseases named in the same sentence as CXCR2 in open-access papers (continued):
Sharing a sentence is not in itself a finding about the gene and the disease.
cancer (continued). "C-X-C motif chemokine receptor 2 (CXCR2) signalling plays an important role in inflammatory diseases and cancer." (PMID 38324085, 2024). "Nevertheless, the chemokine receptor drugs that have demonstrated promising anti-cancer activity in clinical trials, particularly antagonizing CCR2, CCR4, CXCR2, and CXCR4, emphasizes the importance of studying chemokine regulation and receptor mechanisms." (PMID 37006247, 2023). "Many cancer cells exhibit induction or increased expression of multiple ligands for both CXCR1 (CXCL1-3, 5–8) and CXCR2 (CXCL1-3, 5 and 7)." (PMID 37270599, 2023). "The combination of HFD plus cancer resulted in increased expression of some cytokines in the OFB (e.g., Ccl2, Ccl4, Cxcr2, Il1b) and decreased expression of others (e.g., Ccr5, Cx3cl1, eNos, Tnfa) as compared to the HFD group alone." (PMID 38264656, 2023). "We have demonstrated a significant correlation between CXCR2 expression and cancer cell MMP9 in ESCC tissues (p = 0.010) through IHC, and the expression ratio of CXCR2 to CXCR1 was the highest in TE-10 among the three ESCC cell lines on Western blot." (PMID 37296952, 2023). "Therefore, IL-8 and CXCR2 may be important therapeutic targets against cancer." (PMID 37174126, 2023). "Protein expression of CXCL5/CXCR2 and CXCL12/CXCR4 were decreased with KT treatment, resulting in KT inhibiting cancer cells’ secondary growth within the bone." (PMID 36674719, 2023). "In cancer cell-free EC-adjacent tissues (TA), the expression of MYC, NR5A2, SNAI1, and CXCR2 was higher than in Ctrl samples." (PMID 36140779, 2022). "Cancer cell proliferation is stimulated by MSC-derived chemokines CXCL1/2 and CXCL12/SDF-1 that activate signaling pathways dependent on respective CXCR2 and CXCR4 receptors expressed by cancer cells." (PMID 35269887, 2022). "By binding to the receptors C-X-C motif chemokine receptor 1 (CXCR1) and C-X-C motif chemokine receptor 2 (CXCR2), IL-8 promotes cancer angiogenesis and metastasis." (PMID 36497451, 2022). "Due to the contribution of the CCL2/CCR2 and CXCL1/CXCR2 axes to the pathology of various cancers, there have been attempts to develop CCR2 and CXCR2 antagonists, anticipating therapeutic benefits from CCR2 and CXCR2 inhibition." (PMID 36403057, 2022). "Collectively, these results demonstrate that CXCL1/2 and their receptor CXCR2 play key roles in M2 TAMs-induce SOR resistance and cancer stemness in HCC cells." (PMID 36411463, 2022). "CXCR2 upregulation was found in TNBC themselves and was suggested as a novel cancer stem-like cell marker for TNBC." (PMID 36555469, 2022). "However, CXCR2 expression was observed in each cell line suggesting that even with the same receptor and signaling, the functions of IL-8/CXCR2 signaling might be changed depending on the difference in expression level of CXCR2 and the characteristics of the cancer itself." (PMID 35804329, 2022). "The results of TCGA analysis showed that CXCR1 and CXCR2 were lowly expressed in LUAD, and patients with the cancer subtype of magnoid tended to express high level of CXCR1 mRNA." (PMID 35768814, 2022). "Therefore, it may be that CXCR-2 is more involved than CXCR1 in cancer suppression." (PMID 35804329, 2022). "SB225002, a selective CXCR2 antagonist, and SCH-527123, a CXCR1/CXCR2 antagonist, canceled the cancer-promoting effects of conditioned media from senescent hPSCs." (PMID 36012531, 2022). "CXCR2, receptor of CXCL1, is highly expressed on the surface of neutrophils and is involved in progression in several kinds of cancer, such as lung, prostate, breast, colorectal, ovarian, and pancreatic cancer." (PMID 34760697, 2021). "Kaplan-Meier curves also demonstrated the prognostic significance of CXCR2 in OS and DSS of diverse cancer types." (PMID 34840630, 2021). "Cancer cells expressed high levels of ligands CXCL1, CXCL2, CXCL3, and CXCL8, signaling to the receptors CXCR1 and CXCR2 expressed by neutrophils." (PMID 33953163, 2021).
cancer (continued). "CXCL5 exerts its action by binding to its G-protein-coupled receptors chemokine receptor 2 (CXCR2), and the CXCL5/CXCR2 axis has been widely investigated in various types of cancers." (PMID 34603292, 2021). "Several CXCR2 inhibitors (AZD5069, SB225002, SCH-527123, and danirixin) are currently under development for cancer treatment." (PMID 33458757, 2021). "In this context, neutralizing antibodies against CXCR1, CXCR2, or CXCL8 suppressed the migration and invasion in a human ESCC cancer cell model induced by CXCL8." (PMID 33390169, 2021). "However, the specific anti-cancer mechanism of targeting CXCR2 remains unclear." (PMID 33814009, 2021). "For example, administration of the anti-cancer reagent induced CXCL8 production, and the expression of the receptors of CXCL8, CXCR1 and CXCR2." (PMID 32766720, 2020). "In cancer, MIF predominantly signals through binding with the CD74 receptor, however, binding through the chemokine receptors CXCR2, CXCR4, and CD44 have also been shown." (PMID 32317702, 2020). "Thus, inhibiting CXCR2 production may promote cancer cell apoptosis." (PMID 31788042, 2019). "Two other stage-IV specific genes, namely the downregulated CXCR2P1, which is a C-X-C motif chemokine receptor 2 pseudogene 1, and LOC25845, are minimally documented in the literature in the context of HCC, other cancers or any other condition." (PMID 31277598, 2019). "IL-8 has been reported to induce cancer cell invasion by interacting with its receptors, CXCR1 and CXCR2, on the surface of cancer cells." (PMID 31684995, 2019). "Previous studies have demonstrated that CXCL8 and CXCL7 regulated the progression of various cancers via binding to CXCR1 and CXCR2." (PMID 30984000, 2019). "The CXCR2-inhibitory antibody, SB265610, substantially curbs the migration of cancer cells to MSC-conditioned media." (PMID 31788042, 2019). "Interestingly, CXCL5 and CXCR2 protein expression by IHC staining appears more easily detected in cancer cells and bone marrow of IC bone cultures compared to healthy bone cultures and could reflect a higher CXCL5 and CXCR2 protein expression in these cells within IC bone co-cultures." (PMID 31562303, 2019). "CXCR2 is an unfavorable predictor in terms of OS and RFS in patients with cancer except for digestive tract cancer and is related with poorer prognostic." (PMID 29599927, 2018). "Neutrophils from healthy donors and cancer patients had similar expression of the chemokine receptors CXCR1 and CXCR2." (PMID 30323345, 2018). "Unbiased analyses identified cancer-elaborated CXCL1/PPBP, potent myeloid cell chemoattractants that drive inflammation and metastasis via CXCR1/CXCR2 on host cells, as the transcriptional targets of IL-1β-fostered KRAS-IKKα addiction." (PMID 29445180, 2018). "Increased IL-8 of prostate cancer cells signals through CXCR1 and CXCR2 to induce transcription of androgen receptor (AR) and to activate ERK and Akt, in turn, promoting cancer growth and survival." (PMID 29379802, 2017). "Therefore, CXCR2 might play a critical role in cancer progression." (PMID 29312644, 2017). "Among chemokine receptors, CXCR2 mRNA expression was decreased by 12-fold and CXCR4 mRNA expression was upregulated nearly 7-fold throughout cancer progression." (PMID 27143385, 2016). "Use of pharmacological inhibitors and blocking mAbs showed that both CXCR2 and CXCR4 are predominantly involved in the migration of the other cancer models towards Ad-CM." (PMID 26756352, 2016). "Recently, several studies indicated that specific blockade of CXCR1 or CXCR2 with neutralizing antibodies resulted in different inhibition of CSC population and cancer cell growth." (PMID 25871388, 2015). "Although initially described as a selective antagonist of CXCR2, later studies have identified other cellular targets for SB225002, with potential medicinal use in cancer." (PMID 26302043, 2015).
cancer (continued). "During cancer growth, vascularization is a key factor to support the development of tumors, wherein CXCL8 induces endothelial growth through CXCR1 and CXCR2 signaling." (PMID 26087179, 2015). "We found that orospheres overexpressed several genes, such as VEGF, FXYD5 (dysadherin), CXCR2, and MMP10, that have been strongly correlated with invasion and metastasis in many cancers, including H&N carcinomas." (PMID 25428916, 2015). "In monocytes, an increase in CXCR4 expression has been shown in CD14+CD16− cells cultured with cancer cells, alongside increases in the expression of CCR2, CXCR1 and CXCR2." (PMID 25251539, 2014). "Reparexin is a noncompetitive allosteric inhibitor of the IL-8 receptors CXCR1 and CXCR2, and its cytotoxic effects on cancer cells at different concentrations were not significantly different." (PMID 39905539, 2025). "Clinical trials of targeted neutrophil therapies for cancers aim to evaluate the safety, efficacy, and biological impact of novel interventions targeting key molecular pathways such as CXCR1/CXCR2, STAT3, IL-6, TGF-β, and Cluster of Differentiation 47—Signal Regulatory Protein Alpha (CD47-SIRPα)." (PMID 40227814, 2025). "The human chemokine receptor (CXCR2) is a G protein-coupled receptor (GPCR) that gained the attention of the drug discovery community due to its promise as a target for the treatment of various inflammatory disorders and different types of cancer." (PMID 40727104, 2025). "Since drugs targeting CXCR2 have failed to prove effective in the clinic, we reasoned cancer cells expressing high levels of HIF1A or MYC are resistant to CXCR2 inhibitors." (PMID 40050422, 2025). "We therefore tested an alternative Ccr7 inhibition approach using navarixin, a small molecule negative allosteric modulator of Ccr7, Cxcr1, and Cxcr2 that has been studied in clinical trials for airway disease and cancer indications." (PMID 39969509, 2025). "Targeting CXCLs/CXCR2 signaling may be a viable treatment strategy to suppress tumorigenesis and improve the survival outcome of LUAD patients with NKX2‐1‐low malignant tumors." (PMID 39113226, 2024). "In addition to its role in directly recruiting neutrophils, it has been demonstrated that in cancer, CXCL1 also regulates the expression of CXCR2 on the surface of neutrophils." (PMID 38474145, 2024). "There could be a difference in downstream effectors separating CXCR1 and CXCR2, which leads CXCR1 to be a rising cancer stem cell (CSC)-like marker in several solid tumors." (PMID 36831112, 2023). "CXCL1 is known to promote neoplastic transformation, tumorigenesis, and angiogenesis in multiple cancer types by binding CXCR2 (CXCR2 was also increased in our analysis, data not shown)." (PMID 36975480, 2023). "CXCR2 activation also reduces the expression of p21 and increases the expression of cyclins and cyclin dependent kinases such as cyclin A, cyclin B1, cyclin D1, cyclin E, CDK2, and CDK6, thereby promoting the increased proliferation of cancer cells." (PMID 37686093, 2023). "For the various types of cancer featured in this review, collagen I interacts with various receptors on cancer cells (including integrinβ, Endo180 or uPARAP, DDR, LAIR-1, CXCR2 and CXCR4), opening interesting perspectives for the development of new drugs targeting such interactions." (PMID 37373151, 2023). "Additionally, we examined the expressions of IL-8, CXCR1, and CXCR2, which we previously reported, and MMP9 expression of cancer nests in the human ESCC tissues." (PMID 37296952, 2023). "Besides chemokines of NF-κB signaling, the inflammatory cytokines TNF-α and LIF were highlighted to play a role in interaction with CXCL-8 in cancer development and the chemokines CXCL3 and CXCR2 in their role in cell migration." (PMID 37048115, 2023). "This is lightly investigated in TNBC in vitro using CXCR1 or CXCR2 antibodies but was not investigated in each cancer type nor in vivo." (PMID 36831112, 2023).
cancer (continued). "CXCR2 is expressed in many pancreatic ductal adenocarcinoma (PDAC) cell lines, and it is mainly involved in enhancing the proliferation and viability of cancer cells through autocrine or paracrine action." (PMID 37576896, 2023). "CXCR2 is critical for inducing the recruitment and NET formation of neutrophils in cancer." (PMID 36859266, 2023). "For that, we polarized BMDMs with WT 4T1 or E0771 cancer cells and performed Boyden chamber invasion assays with the polarized BMDMs together with WT 4T1 or E0771 cancer cells, with or without the CXCR2 inhibitor SB225002 added to the medium." (PMID 35998057, 2022). "Aberrant expression/signaling of CXCR2 and of its multiple ligands, including several CXC chemokines GRO-α, plays crucial role in carcinogenesis by promoting cancer cell proliferation, migration, and invasion, as well as angiogenesis and by contributing to chemo- and radioresistance in many cancers." (PMID 36140779, 2022). "CXCR2 activation also results in the secretion of epidermal growth factor (EGF) by epithelial cells, VEGF via STAT3 activation, and lymphangiogenic factors such as VEGF-C and VEGF-D by cancer cells." (PMID 35216283, 2022). "From our own findings and prior reports of CXCLs-CXCR2 in cancer progression, we hypothesized that MIF/CXCLs-CXCR2 pathways could be activated by TKI-treatment in viable blasts to support their survival and continuous proliferation." (PMID 35625776, 2022). "Having shown that CXCL1 enhances cancer cell invasion, we asked whether inhibition of the CXCL1 receptor CXCR2 blocked the macrophage-induced invasion." (PMID 35998057, 2022). "To clarify the roles of CXCLs in the cancer-promoting effects of senescence-induced hPSCs, we used SB225002, a selective CXCR2 antagonist, and SCH-527123, a CXCR1/CXCR2 antagonist, to block the CXCLs/CXCR2 axis." (PMID 36012531, 2022). "Next, we investigated the effect of treatment by the small molecule inhibitors EC330 (a small molecule compound that effectively inhibits the function of LIF in promoting the proliferation and migration of cancer cells 31) and SB225002 (targeting CXCR2) on lung metastasis." (PMID 35280694, 2022). "The cancer cell-derived EV were shown to modulate the dissemination pattern of metastatic cells and, in particular, MSC-EV have been seen to stimulate chondrocyte and synovial MSC migration via the CXCL5 and CXCL6/CXCR2 axes." (PMID 36076936, 2022). "Among them, CXCR2 displayed stage-specific expression alterations in STAD, while no clear associations were found in most cancer types." (PMID 34840630, 2021). "CXCR2 antagonists are under investigation as anti-inflammatory therapeutics in a variety of disease states including chronic obstructive pulmonary disorder (COPD), type I diabetes, rheumatoid arthritis, ulcerative colitis, and cancer." (PMID 34944914, 2021). "The combination of CXCL5 and CXCR2 exerts a strong granulocyte chemotaxis and angiogenesis effect, and CXCL5/CXCR2 axis plays an important role in mediating the infiltration and metastasis of malignant tumors." (PMID 33869023, 2021). "The CXCR2 is a specific receptor for CXCL1 and is involved in CXCL1-mediated cancer progress." (PMID 34760697, 2021). "While there are no CXCR2-targeted drugs currently approved for use in cancer treatment, other CXCR2 antagonists are in various stages of clinical development." (PMID 34944914, 2021). "Furthermore, univariate cox regression models were conducted for investigating the correlations of CXCR2 with OS and DSS in each cancer type." (PMID 34840630, 2021). "During cancer progression, cancer cell-derived CCL2, CCL5, CXCL8, and CXCL5 are released and recruit immunosuppressive-myeloid cells into the TME, including MDSCs, TAMs, and TANs through CXCR2 activation." (PMID 35127700, 2021).
cancer (continued). "Given its key role in host defense, the most effective strategies to neutralize the pro-tumorigenic effects of endogenous G-CSF in the setting of adjunctive anti-cancer therapy are likely to involve pharmacologic targeting of the CXCR1 and CXCR2 chemokine receptors." (PMID 33233675, 2020). "Parallel genome-scale loss of function screens in 216 cancer cell lines implicate that IL-8, CXCR1 or CXCR2 knockdown has a negative impact on cell survival and proliferation." (PMID 33277516, 2020). "In contrast, marrow cells in cancer-primed animals either do not express DARC or express excess CXCL5 that can activate CXCR2 expression in the cancer cells." (PMID 31562303, 2019). "The significant strength of our meta-analysis is that fully literature search was conducted and that no previous study illustrated the correlation between CXCR2 and cancers in the form of meta-analysis." (PMID 29599927, 2018). "The analyses of different analysis models (univariate or multivariate models), sample size (< 300 or ≥ 300) and ethnicity (Asian and Caucasian) have indicated the negative impact of CXCR2 over-expression on survival of patients with cancer." (PMID 29599927, 2018). "The cut-off value of each study was different so there was a lack of uniform cut-off values when CXCR2 was used as a predictive biomarker of cancer prognosis." (PMID 29312644, 2017). "The overall survival of patients with CXCL1 and CXCR2-positive cancer was poorer than that of the patients with negative cancer." (PMID 28575019, 2017). "In our study, the expression levels of both CXCR1 and CXCR2 in cancer nests were not related to prognosis." (PMID 29285315, 2017). "Such a concept is supported by our results with other types of cancer demonstrating, at least in vitro, that their migration towards Ad-CM is rather dependent on the CXCR2 and CXCR4 receptors, with no involvement of the CCR3 receptor." (PMID 26756352, 2016). "Our data demonstrate that CXCR2 contributes to IL-1β-mediated EGFR transactivation in OSCC and may provide an explanation for the oncogenic effect of CXCR2 in this cancer." (PMID 26462152, 2015). "Pertinently, the CXCR2 and CXCR4 chemokine receptors are currently among the most promising GPCR targets in anti-cancer drug development, as they are aberrantly expressed in many tumors, where they exert potent proliferative, pro-survival, and pro-migratory effects." (PMID 26041885, 2015). "Since CXCR2 activated AKT signaling to promote the migration and invasion of lymphocytes and cancer cells, we asked whether AKT signaling was also involved in miR-K3 and KSHV induction of cell migration and invasion." (PMID 26402907, 2015). "We then inspected CXCR2 protein expression in cancer and non-cancerous tissues by immunoblotting and immunohistochemistry." (PMID 26087179, 2015). "Thus, CXCR2 is identified as a novel target for therapies aiming to inhibit MDSC recruitment and provides a rationale for combining immune checkpoint inhibitors with agents designed to prevent MDSC-mediated immune suppression in cancer therapy." (PMID 40124384, 2025). "Additionally, some CXCR2 inhibitors, such as danirixin and elubrixin, which were initially developed for treating non-cancer diseases, are being repurposed for cancer treatment with encouraging prospects." (PMID 39780187, 2025). "On the other hand, the time courses of SLC2A1 and CXCR2 indicated disappointing results indicating those markers may not be helpful to monitor the cancer recurrence." (PMID 38514751, 2024).